CDK4 (cyclin dependent kinase 4)
Diseases named in the same sentence as CDK4 in open-access papers (continued):
Sharing a sentence is not in itself a finding about the gene and the disease.
cancer (continued). "The second topology in the pseudo-albino skin comprised highly expressed cancer genes (Cyclin-Dependent kinases Protein (CDK), Chondrosarcoma Kinase (CDK4 cyclin-dependent kinase), Sarcomere protein titin (TTN), Tyrosinase Phosphatase (SHP2)." (PMID 39063015, 2024). "For example, the well-known cancer-related gene CDK4 shows a higher frequency of copy number variations when OCT4 expression is low, while CDK4 expression decreases when the patient’s OCT4 gene expression is upregulated." (PMID 39588508, 2024). "In conclusion, our study reveals a previously unrecognized mechanism for the regulation of YAP stability, suggesting MAP3K3 inhibition as a promising strategy for overcoming resistance to CDK4/6 and BRAF inhibitors in cancer treatment." (PMID 38622197, 2024). "Three CDK4/6 inhibitors have received Food and Drug Administration (FDA) approval and have been integral in advancing cancer treatment." (PMID 39254653, 2024). "To date, CDK4/6 inhibitors and CDK1/2 inhibitors are widely used in clinical therapies or under clinical trials because of their pan-cancer killing effects." (PMID 38963708, 2024). "Combining the findings on the phosphorylation of Rb and CDK4 by CDKL3, we tested the regulatory role of CDKL3 in cancer cell proliferation in vivo." (PMID 38963708, 2024). "Given the pivotal role of the CDK4/6-RB1 pathway in cell proliferation and cancer development, targeting CDK4/6 offers a valuable cancer treatment strategy, potentially arresting the cell cycle in the G1 phase and reducing cell survival." (PMID 39199633, 2024). "These research findings reveal the potential value of using a combination strategy of CDK4/6 and SETDB1 inhibition to reduce RB degradation and suppress cancer growth." (PMID 39048965, 2024). "Despite the modest BBB uptake, [18F]NT431 represents an important step towards the future evaluation and development of CDK4/6 inhibitors or radioligands with superior BBB penetration for treatment and visualization of CDK4/6 positive cancers in the CNS." (PMID 38999983, 2024). "Cyclin D1 is an important cell cycle regulatory protein responsible for activating CDK4 and CDK6 kinase activities and promoting cancer cell proliferation." (PMID 39768127, 2024). "In many cancers, including CCA, overexpression or dysregulation of CDK4/6 leads to increased cell proliferation." (PMID 38730642, 2024). "The aggarwal group ascertained that cyclin D1T286A, CDK4, MEP50 and PRMT5 coprecipitate in B cells and human cancer cells." (PMID 39255317, 2024). "All ATRT cell lines depend either on CDK4 or CDK6 expression in a mutually exclusive manner, a pattern recapitulated by most human cancer cell lines, and most require expression of at least one out of three D-type cyclins." (PMID 39617889, 2024). "This, coupled with the observed suppression of cyclin-dependent kinases (CDKs) CDK4 and CDK6 expression, hints at the crucial role of CDKs in BTZ’s anti-cancer effects." (PMID 38724504, 2024). "A possible explanation for its oncomiR function in this setting might derive from non-cancer models such as ARDS, where miR-877-5p suppressed CDKN1B which encodes p27Kip1, whose downregulation is claimed as one of the possible mechanisms of resistance to CDK4/6i." (PMID 38338777, 2024). "We also interrogated the response of the cancer organoids to HZ1 with the genetic modulations of CDKL3, CDK4, or Rb." (PMID 38963708, 2024). "In conclusion, CARM1 is a potential cancer biomarker and CARM1, HIF1A, and CDK4 are positively correlated in multiple cancers." (PMID 38476024, 2024). "Glabridin inhibits cancer cell proliferation and survival by downregulating cyclin D3, CDK2, and CDK4, blocking the G1/S phase transition, and reducing CREB and ATF1 phosphorylation." (PMID 39723390, 2024).
cancer (continued). "Given the increasing clinical use of inhibitors to CDK4/6, MEK, and PD-L1 in cancer patients, either as monotherapies or in combination strategies, finding new targets to combat resistance to these agents is of significant interest." (PMID 39347707, 2024). "The aim of this study was to develop a novel CDK2 inhibitor to provide a new therapeutic option for cancer patients with CCNE1 overexpression and resistance to CDK4/6 inhibitors." (PMID 38338471, 2024). "The most commonly overexpressed genes in rare cancers included BIRC5 (88%), TOP2A (85%), CDK4 (82%), BRIP1 (76%), MSH6 (66%), and HDAC2 (62%)." (PMID 38347552, 2024). "Among these regulators, CDK-4 and CDK-6 play pivotal roles and are frequently dysregulated in various human cancers." (PMID 38611854, 2024). "The efficacy of this agent in preclinical models of both CCNE1-amplified and CDK4/6i–resistant cancers was encouraging and supported the rationale for targeting CDK2 in cancer, but its clinical development has been discontinued." (PMID 38047585, 2024). "Pharmacological inhibitors targeting CDK4/6 have been developed based on the rationale that inhibiting CDK activity will block cell proliferation, thereby mitigating cancer pathogenesis." (PMID 39501082, 2024). "In the realm of cancer treatment, CDK 4/6 inhibitors (CDK 4/6i) are employed to target overactive CDK4/6-cyclin D complexes." (PMID 38464732, 2024). "Cyclin-dependent kinase-4 and cyclin-dependent kinase-6 (CDK4 and CDK6) are often overexpressed in cancer, including CRPC, and are considered as targets for cancer treatment." (PMID 39090086, 2024). "WB detected protein expression levels of CDK4, CDK6 and cyclin D1, which were key cell cycle proteins for cancer proliferation." (PMID 38195969, 2024). "Recent studies have highlighted the complex interactions between CDK4/6, HIF1α, and SMURF2, particularly in regulating HIF1α stability, which has significant implications for cancer progression." (PMID 39697237, 2024). "D-type cyclins activate CDK4 and CDK6, which subsequently phosphorylate and inactivate the RB1 tumor suppressor, thereby derepressing cancer cell proliferation." (PMID 39664374, 2024). "Our study reveals a mechanism responsible for CDK4/6i resistance and provides an enlightening approach to investigating the combinations of CDK4/6 and LRPPRC inhibitors in cancer therapy." (PMID 37452037, 2023). "Despite significant advancements in cancer treatments, patients with metastatic breast cancer (MBC) remain incurable, with a median overall survival (OS) of approximately five years with CDK4/6 inhibitor based therapy." (PMID 37046675, 2023). "Among these potential druggable alterations, EGFR, KRAS, and PIK3CA gene alterations were the most common, while CDK pathway (CDK4/6, CDKN2A/2B), FGFR1/2/3, BRAF, RET was uncommon across pan-cancer." (PMID 36910668, 2023). "Among them, the cyclin D-cyclin dependent kinase 4/6-inhibitor of CDK4-retinoblastoma (cyclinD-CDK4/6-INK4-RB) is an essential pathway for cancer cells to modulate G1 to S, which is important for many cancer types’ initiation, development, and survival." (PMID 38293701, 2023). "Pharmacologic inhibitors of CDK4/CDK6 result in G1 phase cell cycle arrest, suppressing cancer cell proliferation." (PMID 35789211, 2023). "As an inhibitor of CDK4/6, PAL is widely used in targeted cancer therapy to induce G0/G1 cell cycle arrest." (PMID 36852326, 2023). "In sum, we propose that the current work describes a defective cell cycle pathway with cancer-like properties involved in AVM development and identifies anti-cancer CDK4/6 inhibitors as potential therapeutics for HHT." (PMID 37745444, 2023). "CDK4/6 and CDK2 are the dominant CDKs that control cell G1/S transition though finely tuned regulation of the phosphorylation of the Rb cancer suppressor, which subsequently releases E2F, a transcriptional factor involved in cell cycle regulation." (PMID 37563111, 2023).
cancer (continued). "The expressions of CDK4/6 and c-Myc in 31 cases of SCLC cancer tissues and paired adjacent normal tissues were analyzed by immunohistochemistry." (PMID 36872049, 2023). "We further investigated the expression and distribution of proliferation-related (CDK4, MKI67) and cancer-related epithelial (KRT15, CD24) cell marker genes among each cluster." (PMID 36811599, 2023). "For instance, palbociclib, an inhibitor of the cyclin-dependent kinases CDK4 and CDK6 used in HR+/HER2- cancer treatment, has been observed to directly bind to and inhibit STING." (PMID 38139802, 2023). "Analysis of RNA-seq data of Cdk4−/− and Cdk6−/− cancer cells revealed that the MCM and DNA polymerases are downregulated in Cdk4−/− cells while DNA polymerases were decreased in Cdk6−/− cells, which was validated by qPCR assay." (PMID 37833461, 2023). "In particular, the targeting of cell cycle progression has advanced greatly with the development of CDK4/6 inhibitors that are now in clinical use for HER2+ breast cancer and are under investigation for the treatment of a variety of Rb1+ cancers." (PMID 37484531, 2023). "The downregulation of the PI3K/AKT pathway by fucoidan contributed, in part, to a reduced expression of CDK-4, CDK-6, cyclin-E, and cyclin-D1, consequently halting cancer cell growth while inducing the apoptosis of the cancer cells." (PMID 38248653, 2023). "These include anesthetics, anti-amyloidogenics, antidiabetic, potent mineralocorticoid receptor antagonists, dual MDM2 and CDK4 inhibitors targeting glioblastoma, anti-cancer agents towards HCT-116 and MCF-7 cancer cells." (PMID 37959862, 2023). "Based on these results, CDK1, CDK2, CDK4, CDK5, and CDK7 are the top 5 CDKs that are highly expressed in cancer tissues compared to normal tissues." (PMID 37311884, 2023). "However, promising treatment outcomes of CDK4 inhibitors were only observed in HPV-negative HNSCC rather than HPV-positive HNSCC due to the mutation differences of cell cycle-related genes in cancer cells, and less attention has been paid to the effects of CDK4 inhibitors on infiltrating T cells." (PMID 36811599, 2023). "In this regard, formononetin has been shown to have a significant contribution in cancer inhibition through cell cycle arrest by affecting different cell cycle mediators, such as cyclin D1 and cyclin DK4 (CDK4)." (PMID 37298670, 2023). "CDK4, AKT, and HER2 are involved in cell proliferation, indicating that these molecules would be promising targets for cancer therapy." (PMID 37615898, 2023). "In recent years, kinase inhibitors targeting CMGC kinases, such as CDK4/6 inhibitors and BRAF/MEK inhibitors, have demonstrated clinical success in treating specific cancer types." (PMID 37568654, 2023). "Overall, compared with normal tissues, the expression of CDK4 and CDK5 are higher in 18 out of 24 or 75% of the cancers listed." (PMID 37311884, 2023). "CCND1 is a downstream effector in the Wnt2/β-catenin pathway and activates the cyclin-dependent kinases (CDKs) CDK4 and CDK6 to promote cancer proliferation." (PMID 37056769, 2023). "Sunitinib was identified as one of the most promising drugs in both A375 and SK-MEL-28 cells, in addition to CDK4/6 inhibitors, which have been reported to synergize with BET inhibitors in cancer cells, thus supporting the validity of our screen." (PMID 36720918, 2023). "Since dysregulated cell cycle regulation is considered one of the hallmarks of cancer, CDK inhibition for therapeutic purposes, especially CDK4/6 using small molecule inhibitors, presents a convincing solution for overcoming resistance to conventional drugs." (PMID 36769170, 2023).
cancer (continued). "Cyclin-dependent kinase 4 (CDK4) and CDK6 are dysregulated in cancer cells and many preclinical studies have demonstrated the hyperactivity of the cyclin D–CDK4/6 axis, rendering CDK inhibitors as desirable therapeutic approaches." (PMID 37190065, 2023). "This study provides new insights of SEMA6C-mediated anti-cancer action and suggests the treatment of SEMA6C-downregulated cancer by CDK4/6 inhibitors." (PMID 35269749, 2022). "Cyclin-dependent kinase 4 (CDK4) is an oncogene that is particularly important for controlling the cell cycle and has been demonstrated in many types of cancer." (PMID 36139487, 2022). "The intervention of CDKs has been a hot topic in cancer therapy, among which inhibitors that block the activity of CDK4 and CDK6 enzymes (CDK4/6) have been approved by the FDA to treat metastatic hormone receptor-positive breast cancer." (PMID 36082129, 2022). "Thus, the molecular mechanisms by which CDK4/6 inhibitors induce senescence in cancer cells and the genes involved in conferring drug resistance or lack of response to these inhibitors are unknown, preventing patient stratification prior to Palbociclib treatment." (PMID 35184131, 2022). "BET inhibitors reduce expression of multiple DNA replication genes, including AURKA, AURKB, CDK4 and CCND1, in multiple cancer types, including TNBC." (PMID 36139513, 2022). "The development of selective inhibitors, of both CDK4 and CDK6, has markedly changed the perception of CDKs as therapeutic targets in cancer." (PMID 35053461, 2022). "Overall, FDLE was able to strongly suppress cancer cell growth in HCT-116 cells by decreasing growth-related proteins such as cyclin D1 and CDK4 and increasing p21 through the mechanism of inhibition of NF-kB signaling pathway." (PMID 35681644, 2022). "Frequent copy‐number aberrations were also found for important cancer genes, such as CDKN2A, KIT, MDM2, CCND1, CDK4, and PAK1, among others." (PMID 35229492, 2022). "CDK4 and CDK6 are targets for cancer therapies because they are part of the CCND–CDK4/6–CDKN2A–Rb pathway, which mediates the cell cycle transition from G0/1 to S phase." (PMID 36033522, 2022). "In non-cancer cells, RB1 is dephosphorylated by the cyclin-dependent kinase 4/6 (CDK4/6) pathway and can bind the transcription factor E2F, which prevents cell division." (PMID 34687436, 2022). "Thus, CDK4/6i + RT may be a viable therapeutic strategy in other cancer types." (PMID 34932500, 2022). "The cross talk between the cyclinD1-CDK4/6-pRb axis and PI3K/AKT/mTOR pathway has always been regarded as more obvious in hormonal receptor-positive and HER2-positive cancers, as ER can directly target cyclin D1 transcriptionally and activate CDK4/6-pRb." (PMID 36387174, 2022). "Some members of CDK family including CDK1, CDK2, CDK4 and CDK6 have been reported to be involved in the regulation of cell cycle, thus participating the development and progression of cancer." (PMID 35517403, 2022). "The whole-exome sequencing of osimertinib-resistant patient-derived cancer cell lines revealed amplification of GLI1, CDK4, and CCND1." (PMID 35584089, 2022). "SHP2, ITK, VRK2, PTPN2, GSK-3, CDK4/6, and PAG all have evidence supporting their relationship to the PD-1 pathway in T cells and pro-tumorigenic role in cancer cells." (PMID 35911672, 2022). "CDK4 and CDK6 are essential regulators of the initial phases of the cell cycle and are a promising anti-cancer treatment option." (PMID 35885460, 2022). "As kinases, CDK4 and CDK6 play a crucial role in the G1-S phase transition, which is an important restriction point in the normal cell cycle, often reduced in cancer, leading to uncontrolled cell proliferation." (PMID 36505864, 2022).
cancer (continued). "Palbociclib is the first CDK4/6 inhibitor approved by FDA and has been studied in many types of cancer." (PMID 37181790, 2022). "CDK4 and CDK6 are crucial for cell cycle regulation and are attractive targets for the treatments of various types of cancers, including GB, frequently characterized by a CDK4/6 pathway dysregulation." (PMID 35242765, 2022). "Since the majority of cancer cells have an intact RB1 gene and thus depend on CDK4/6 kinase activity for sustained proliferation, CDK4/6 emerged as a potential target for cancer therapy." (PMID 36067171, 2022). "The literature discussed here was obtained from a search of the published literature and ClinicalTrials.gov with the following key terms: checkpoint inhibition, cancer immunotherapy, PD-1, PD-L1, SHP2, PTPN2, ITK, VRK2, CDK4/6, GSK-3, and PAG." (PMID 35911672, 2022). "The pharmacological inhibition of CDK4 interfered with BCSC self-renewal, promoted the transition to an epithelial phenotype and eliminated chemotherapy-resistant cancer cells." (PMID 34778245, 2021). "Multiple cancer-related PROTACS have been developed so far, and these include PROTACS directed at EGFR, CDK4/6, ERK1/2, and PI3K." (PMID 33809714, 2021). "First, CDK4/6 inhibitors have been shown to increase Type III interferon production and cancer antigen presentation." (PMID 34071228, 2021). "Previous analyses of gene expression profiles in several cancer cells also showed that selenium specifically downregulated CYCLIN A, CYCLIN D, CDC25A, CDK4, and other cell cycle-related genes to induce cell cycle arrest." (PMID 34094961, 2021). "For example, in different cancer types the let-7 miRNA family alone modulates the abundance of CCND1, CDK4 as well as MYC." (PMID 33748099, 2021). "The discovery of these roles of CDK4 and CDK6 in several cellular processes has certainly positively contributed to the further clinical development of CDK4/6i in different types of cancer, used alone or in combination with other therapeutic approaches." (PMID 34204543, 2021). "In preclinical cancer models, continuous inhibition of CDK4 and CDK6 by abemaciclib led to cell cycle arrest and death of cancer cells." (PMID 33797023, 2021). "Using bioinformatics, we successfully identified CCND1/CDK4/PLK1/CD44 as oncogenic signatures, which drives cancer progression and resistance to treatment, and as potential druggable candidates for both NSC7565600 and NSC765691 small molecules." (PMID 34063946, 2021). "In summary, combined targeting of CDK(s) (CDK1 or CDK4/6) and HSP90 remarkably inhibits the expression level of HIF1α and shows promising anti-cancer efficacy with therapeutic potential." (PMID 34686682, 2021). "Preclinical models looking for synergy have shown positive effects combining CDK4/6i with inhibitors targeting molecules such as EGFR, MEK, mTOR or BRAF V600E in various cancers, as well as the ability to overcome resistance." (PMID 34138895, 2021). "The transcription factor c-Myc plays an important role in the regulation of cell cycle through modulating cell cycle controllers, such as CDC25A, CDK4, CDK6, Rb, and p-Rb in cancer cells." (PMID 33572615, 2021). "This suggests that the cancer cell activity was reduced, and the p-ERK1/2 and cyclin D1/CDK4/6 axis was involved in the development of CRC." (PMID 34434893, 2021). "It has been reported that the abnormal levels of CDK4, CDK6, and cyclin D1 in various human cancer cells are closely related to the abnormal proliferation of cancer cells." (PMID 34574146, 2021). "In our studies, we found that modulation of the EMT status of cancer cells by perturbing the ZEB1/miR-200 axis led to CDK4 pathway modulation and determined the sensitivity to CDK4 inhibitors both in vitro and in vivo." (PMID 34309585, 2021). "Firstly, CDK2, CDK4, and CDK6, these three CDKs are often all elevated in clinical patient samples of many cancers." (PMID 33579185, 2021).